IGF1R (insulin like growth factor 1 receptor)
Diseases named in the same sentence as IGF1R in open-access papers (continued):
Sharing a sentence is not in itself a finding about the gene and the disease.
tumor (continued). "MiR-497 may influence tumor cell responsiveness to chemotherapy and tumor cell resistance to EGFR-TKI via IGF1R targeting and AKT activation." (PMID 35264191, 2022). "Indeed, KRAS mutated tumor cells induced stromal cells to secrete IGF1 and GAS6 that in turn activated IGF1R and AXL signaling in tumor cells, leading to increased mitochondrial performance, proliferative capacity, and resistance to apoptotic stimuli." (PMID 36324182, 2022). "A monoclonal antibody against IGF-1R, AMG-479, and its kinase inhibitor, MK0406, effectively inhibit the proliferation of ovarian tumor cells and enhance tumor sensitivity to chemotherapeutic drugs such as cisplatin and taxane, which indicates that IGF-2 is an effective target for cancer therapy." (PMID 36358907, 2022). "It is also interesting that in our prior study we showed that Wnt1 tumor epithelial cells increase tumorsphere formation frequency in non-adherent conditions after IGF1R inhibition." (PMID 36568144, 2022). "Because HER2, IGF1R, MET and NTRK2 are also present in tumor-derived exosomes that play important roles in tumor progression, we aimed to investigate whether RAB31 control these RTKs entry into CD63-positive MVEs." (PMID 32958903, 2021). "The lack of clinical success of these trials implies that targeting just IGF-1R is not enough to overcome tumor growth." (PMID 33829018, 2021). "It specifically binds to IGF-1R, triggering downstream mitogen-activated protein kinase (MAPK) and phosphoinosyl 3 kinase/protein kinase B(PI3K/Akt) signal transduction, thus regulating tumor cells growth, proliferation, invasion and metastasis." (PMID 34837929, 2021). "HCC with down-regulated IGF1R led to an increase of C-C motif chemokine ligand 5 (CCL5) secretion, which may function as a chemotactic factor for immune cell in a tumor microenvironment." (PMID 33803804, 2021). "Interestingly, the proteoglycan decorin acts as a tumor suppressor by binding and negatively regulating IGF1, IGF2, insulin, IGF1R and IR-A activity." (PMID 34440844, 2021). "Furthermore, IGF1R silencing mimicked the tumor-suppressive effects of miR-532 in CRC cells, further confirming its direct interaction with IGF1R, and miR-532 overexpression inhibited PI3K/AKT pathway activation both in vitro and in vivo." (PMID 34484116, 2021). "YAP, IGF-1R, and EMT markers (VIMENTIN, SNAIL1, and N-CAD) were visibly expressed in tumor tissues." (PMID 34359714, 2021). "Notably, another finding has suggested that there are complex interactions between CAFs, tumor cells, and IGF/IGF-1R signaling." (PMID 33669204, 2021). "IGF-1R signaling promotes malignant transformation and tumor progression in non-cancerous cells and decreases tumor sensitivity to hypoxia, low pH, and low glucose environments." (PMID 34359752, 2021). "Moreover, the inhibition of EWS-FLI1 fusion protein decreased IGF-1 and impaired the IGF-1/IGF-1R signaling correlated with increased EWS cell apoptosis, reduced migration, and repressed tumor xenograft growth in a mouse model." (PMID 34069554, 2021). "Researchers have found that IGF-1R/IRS1 signaling pathway is also related to the adhesion process among malignant tumor cells, and plays an important role in the phenotype maintenance of cancer cells and the process of anti-tumor treatment resistance." (PMID 34837929, 2021). "It is understood that the AKT pathway could be reactivated despite IGF-1R downregulation, mediated by anti-IGF-1R antibody or TKIs, leading to tumor progression." (PMID 33829018, 2021). "Dysregulation of IGF/IGF-1R signaling in HCC may activate expression of cancer stemness that leads to TKI refractoriness and tumor recurrence." (PMID 33669204, 2021). "For in vitro studies, the role of IKBKE, IGF1R, NOTCH3 and MDM4 in tumorigenesis and tumour metastasis have been reported and have provided clinicians with potential insights for understanding the biological behaviour of TNBC and exploring treatment strategies for heavily treated patients." (PMID 34396843, 2021).
tumor (continued). "Besides demonstrating in vivo anti-tumor activity of rapamycin and sunitinib, RT2 mice have helped rule out pathways with low clinical relevance in pNETs, such as IGF-1R." (PMID 34199469, 2021). "Furthermore, overexpression of FGF12, FGF14, FGF17, FGFR1, FGFBP3 and IGFBPL1 genes was found in early tumor stage, while, overexpression of IGF1R, IGF2BP2 and INSRR was found in advanced tumor stages." (PMID 34061869, 2021). "Therefore, a promising approach is represented by small carrier proteins able to interact specifically and with a high affinity (in the picomolar to the nanomolar range) with several targets overexpressed in tumor cells such as HER2, EGFR, and IGF-1R." (PMID 34439990, 2021). "The presence of nuclear IGF‐1R was initially described in human tumour cells and no malignant tissues characterized by a high proliferation rate." (PMID 32894655, 2021). "Among 49 RTKs, IGF-1R phosphorylation was increased after osimertinib exposure in AXL-low-expressing tumor cell lines, but not in AXL-high-expressing tumor cell lines." (PMID 32929081, 2020). "As compared to the tumor, normal cells with low proliferation showed formation of γH2AX but no IGF1R/PCNA colocalization." (PMID 32701997, 2020). "We believe that the IGF1R/PCNA interaction is a basic cellular mechanism to increase DNA stress tolerance during proliferation, but that this mechanism is lost with tumor progression in conjunction with accumulated DNA damage and aberrant strategies to tolerate genomic instability." (PMID 32701997, 2020). "Compared to tumor OPCs transfected with nonspecific sgRNA, those with sgRNAs specific to IGF1R were largely depleted from the tumor." (PMID 33173731, 2020). "Up to now, IGF1R directed antibody therapy of tumor entities other than CRC showed no promising results in clinical trials." (PMID 32727431, 2020). "Compounds 460–462 showed strong cytotoxicity against six HTCLs (HCT-116, HepG2, BGC-823, NCI-H1650, A2780, and MCF7) (IC50 = 1.3–12.5 μM) and exhibited selective significant inhibitory activity towards the human tumor-related protein kinases of FGFR3, IGF1R, PDGFRb, and TrKB (IC50 = 2.6–21.4 μM)." (PMID 32570903, 2020). "Similarly, miR-217 directly targeted insulin-like growth factor 1 receptor (IGF1R) and suppressed EOC cell proliferation, colony formation, invasion, and migration, as well as inhibited subcutaneous tumor growth." (PMID 32993038, 2020). "Furthermore, a combination of IGF-1R inhibitor (BMS-754807) and MEK inhibitor (U0126) significantly suppressed cell viability and colony formation in cultured cells and tumor growth in mice." (PMID 32843616, 2020). "Low IGF1R expressing tumor cells with a faint, but evident, immunostaining were not to shift the balance to the same extent as unambiguously high IGF1R expressing cells." (PMID 32727431, 2020). "There was no clear association between IGF1R/PCNA colocalization and tumor proliferation as determined by mitotic count (data not shown)." (PMID 32701997, 2020). "Additionally, these compounds presented potent inhibition against the tumor growth-related tyrosine multiple kinase targets FGFR3, IGF1R, PDGFRb, and TRKB at a concentration of <10.4 μM, except for 151, which showed weak activity, with IC50 > 25 μM." (PMID 32570903, 2020). "IGF-1R exhibits crosstalk with EGFR and mediates tumour resistance to EGFR inhibitors, and a phase II clinical trial (NCT00769483) showed that MK-0646, an IGF-1R antagonist, synergistically improved OS when applied with gemcitabine (10.4 months vs 5.7 months, P value = 0.02)." (PMID 33008426, 2020). "Oral administration of AE for 4 weeks caused a significant regression of mouse xenograft tumor (>60%) that derived from OV4855 cells and decreased the expression of endothelial cell antigen-CD31, HIF-1α, IGF1R and SNAIL1 and increased the expression of E-cadherin in tumor tissues." (PMID 32194804, 2020).
tumor (continued). "Furthermore, the adoptive transfer of chimeric antigen receptor (CAR) T cells targeting the IGF-1R and ROR1 significantly reduced tumor growth in xenograft models." (PMID 32630642, 2020). "CRC samples which exhibited cytoplasmic as well as membranous IGF1R expression in less than 10% of all tumor cells were regarded as IGF1R negative." (PMID 32727431, 2020). "However, combining IGF-1R inhibitors with BET inhibitors, or mTOR inhibitors, presents a synergistic effect on the inhibition of survival and tumor growth of ES cells both in vivo and in vitro." (PMID 32754598, 2020). "In the current study, we found that combinatorial therapy of PPP1R1A and IGF-1R inhibitors is superior to single treatment not only in limiting tumor growth but also lung metastasis which has never been reported in prior studies." (PMID 32477459, 2020). "They assessed circulating interleukin-6 (IL-6), VEGF, fasting insulin, and tumor expression of insulin-like growth factor-1 receptor (IGF-1R), insulin receptor (IR), insulin-like growth factor-1 (IGF-1), and RAGE markers before surgery and 6 months after tumor surgery." (PMID 33117687, 2020). "Furthermore, activation of IGF-1R and mTOR and expression of EWS-FLI1 were strongly correlated with high BMI-1 levels, which is overexpressed in 80% of ES patients and induces tumor growth in a xenograft model." (PMID 32754598, 2020). "In these three cases, our results showed a repression of IGF-1R in response to LA compared with non-treated tumours or 2% absolute ethanol condition." (PMID 31988347, 2020). "If IGF1R is not (overly) expressed by the tumor, it is probably not meaningful to use IGF inhibitors, as the pathway is probably not involved in tumor genesis, growth and therapy resistance." (PMID 33260481, 2020). "Compared to no treatment, AG1024 significantly inhibited tumor growth and induced a decrease in Ki67 expression, indicating the great therapeutic potential of IGF-1R inhibitors in the treatment of DLBCL." (PMID 32546241, 2020). "However, IGF-1R and RAGE expressions were increased in tumor tissues; also, fasting insulin levels in CRC patients with metabolic syndrome were significantly enhanced." (PMID 33117687, 2020). "However, tumor uptake of 111In-cixutumumab was significantly higher (p < 0.0001) than 111In-cixutumumab-PEG6-DM1-High, indicating a lower binding to IGF-1R of the radioimmunoconjugate in vivo." (PMID 33122707, 2020). "Although 2-DG has the ability to target glycolysis, its potential to be used as an anti-tumor drug is limited because 2-DG also stimulates the PI3K/Akt, MEK/ERK and insulin-like growth factor 1 receptor (IGF1R) pathways, promoting a survival signal in tumor cell lines." (PMID 31261749, 2019). "Taken together these findings suggest that through IGF1R, HS6ST3 could affect both CCL5 levels and tumor infiltrating CD8+ T lymphocytes behavior." (PMID 31921621, 2019). "Interestingly, we found that knockdown of DLEU1 significantly inhibited DLEU1 expression, increased miR‐133a expression, and inhibited IGF‐1R expression and its downstream PI3K/AKT pathway in xenograft tumours." (PMID 31207081, 2019). "The IL-6-STAT3 mediated IGF-1/IGF-1R signaling or DNMT3b-OCT4-DNMT1 regulation in HCC may be two of the multiple factors involved in stemness expression and tumor recurrence." (PMID 31771617, 2019). "Because suppression of HR sensitizes human tumor cells to IGF-1R inhibition, IGF-1R might be crucial for HR repair of DSBs." (PMID 30621219, 2019). "In opposition to the studies confirming distinct roles of AKT1 and AKT2 in cell proliferation and tumor growth, Watson and Moorehead attribute AKT1 knockdown as well as AKT2 knockdown to a suppressing effect on tumor initiation and growth of an IGF1R-positive breast cancer mouse model." (PMID 31752925, 2019).
tumor (continued). "The transfer of macrophage endogenous miR-223 reduced the expression of IGF-1R in a HCC cell line and inhibited their development, indicating that intercellular transfer of miRNAs could act as a new defense against tumor development." (PMID 31847392, 2019). "Here, we show that GSTZ1‐1 serves as a tumor suppressor in HCC and provide an alternative mechanism by which an oncometabolite may activate the IGF1R pathway." (PMID 31267557, 2019). "For instance, phase II or III trials evaluating the use of the anti-IGF1R mAbs ganitumab, dalotuzumab, and figitumumab were halted after showing no discernible anti-tumor activity or survival benefit." (PMID 30653502, 2019). "In colorectal cancer (CRC), down-regulation of miR-497 caused by the DNA copy number reduction of chromosome 17p13.1 would up-regulate the IGF-1R or IRS1, and activate PI3K/Akt signaling, contributing to the survival of CRC cells by promoting tumor growth and resistance to chemotherapy." (PMID 31847392, 2019). "In addition, we also investigated the effect of DLEU1 on IGF‐1R expression and its downstream PI3K/AKT pathway in xenograft tumour." (PMID 31207081, 2019). "g, MET FISH- was identified as disomy; h, MET CNV = 5.8 and high polysomy ≥ 4 copies in 67% of tumor cells were considered as MET FISH+; i, MET CNV = 12/chr7 CNV = 5.4 with ratio = 2.22 is determined as MET amplification; (j-k) The detection of IGF1R status using FISH in NSCLC patients." (PMID 30823937, 2019). "Moreover, the targetable signalling pathways IGF1R, NOTCH and mTOR were upregulated in AFP-high tumours." (PMID 31285588, 2019). "We measured the proliferation of the IGROV1Res and OAW42Res tumor cell lines treated with increasing concentrations of GDC0032, in the absence or presence of inhibitors such as AEW541 (IGF1R inhibitor), PHA-665752 (MET inhibitor), MK2206 (AKT inhibitor), and others." (PMID 30237504, 2018). "In order to determine if targeting different components of the IGF-1/RhoA/ROCK crosstalk between BC cells and CAFs would affect primary tumor growth and metastasis, we treated MDA-MB-231 xenografts with the IGF-1R inhibitor PQ401, Y27632 or PQ401 combined with Y27632." (PMID 29535813, 2018). "The decrease in CD8+ cytotoxic T cells indicates fewer immune cells responsible for tumor degradation present within the primary tumors lacking IGF-1R function." (PMID 30458886, 2018). "Here we focused on the correlation of myeloid IGF1R, IRS1, and GRB10 with human tumor progression." (PMID 29973593, 2018). "Conversely, IGF-1R expression decreases with cancer de-differentiation, suggesting that the IGF-2/IR-A loop exerts a more important role than the IGF-1/IGF-1R loop in thyroid cells de-differentiation, stemness, tumor progression, and metastasis." (PMID 30513575, 2018). "This identifies another route that miR-376 may serve as a tumor suppressor, as it would be able to directly target and suppress CAV1, IGF1R, or both, to disrupt their oncogenic mission." (PMID 30042829, 2018). "Increased collagen levels measured by Masson’s Trichrome staining revealed that tumors lacking a functional IGF-1R have a significantly altered tumor microenvironment that is consistent with promoting tumor cell invasion." (PMID 30458886, 2018). "The small differences by expression of IGF-1R in tumor tissue were not significant (37.5% [95% CI 26.2–48.9%], 40.7% [95% CI 30.9–50.6%], and 34.7% [95% CI 24.4–45.0%])." (PMID 30497427, 2018). "Indeed, the mRNA and protein expression of IGF1R, IRS1, and GRB10 was increased in Gr-1+CD11b+ cells sorted from spleens of 4T1 tumor-bearing mice compared with that from healthy control mice." (PMID 29973593, 2018).
tumor (continued). "Treatment with IGF1R inhibitors (AG1024, PPP) and IGF1R/IR inhibitor (OSI-906) reduced the viability and induced apoptosis in CLL cells in vitro, independent of the presence of protective stromal cells, and reduced tumor burden in vivo." (PMID 30328953, 2018). "Frequent injections with insulin analogues that only mildly activated the IGF1R in vivo (glargine and insulin) did not significantly decrease the tumor latency time in this mouse model." (PMID 28173837, 2017). "When BRAF is blocked, tumor cells may increase PDGFR-β and IGF-1R expression, leading to persistent PI3K/AKT-signaling that prevents apoptosis and promotes survival." (PMID 29100459, 2017). "IGF1R together with IGF2 may form a short, very active, autocrine loop that is greatly responsible for tumour genesis, as well as intensive proliferation and progression of RMS." (PMID 28793874, 2017). "IGF-1R activation and overexpression promote EMT in many tumor types." (PMID 29212236, 2017). "Insulin-like growth factor binds to 2 receptors, IGF1R and IGF2R, but IGF2R is a tumor suppressor." (PMID 29241458, 2017). "Frequent injections with insulin glargine, a compound that only mildly activates the IGF1R in vivo, showed a similar trend but the observed tumor latency time decrease was not significant compared to regular insulin." (PMID 28173837, 2017). "The activation of IGF1R and IR heterodimers stimulates downstream effectors in the mitogen-activated protein kinase (MAPK) and/or phosphatidylinositol 3-kinase (PI3K) AKT/protein kinase B (PKB) pathways resulting in tumor progression." (PMID 29099049, 2017). "It was reported that miR-223 is a tumor suppressor miRNA, which could suppress LLC by targeting insulin-like growth factor-1 receptor." (PMID 28924214, 2017). "By these targets, Trop2 could maintaining tight junction integrity 5; increases tumor proliferation through activated the NF‐kB, cyclin D1 and ERK; and suppresses IGF‐1R signaling." (PMID 28256068, 2017). "In tumor lesions, the local expression of CCL5 negatively affected the expression of IGF1R." (PMID 29156819, 2017). "In this study, IGF1R mRNA expression level was not correlated with tumor size, lymph node status, and staging of the tumors." (PMID 26884344, 2017). "Further, MEK inhibition blocked the ability of GDF15 to induce tumor sphere formation, indicating that MEK activation downstream of IGF-1R activation may contribute to GDF15-stimulated EMT." (PMID 29212236, 2017). "The increased bioavailability of IGFs may contribute to tumor progression through the stimulation of IGF-1R, IR/IGF-1R hybrids, and IR-A itself." (PMID 29184536, 2017). "Studies carried out with animal models suggested that hyperactivation of IGF1R/mTOR signaling pathway may promote hepatocarcinogenesis, while blocking this pathway showed promising reduction of HCC tumor growth." (PMID 28624790, 2017). "However, the possibility that the frequency was underestimated still remains, because low percentage of MRAS mutation alleles or low copy‐number gain of IGF1R in the tumor tissues of Type IV with low tumor cell contents could not be detected by Sanger sequencing or qPCR, respectively." (PMID 27891760, 2017). "Since IGF1R is not expressed by stromal cells but only by epithelial tumor cells, we compared the stromal infiltration of tumors with the highest and lowest expression of IGF1R, as assessed by RPPA, in our CIT-series for which HE staining are available." (PMID 28882129, 2017). "A heat map of gene expression levels in tumors, ordered in descending order, on the basis of the phosphorylated IGF1R signal, provided a visualization of the expression profile of IGF pathway genes in each tumor, and highlighted the mutually exclusive nature of IGF1 and IGF2 expression." (PMID 28882129, 2017). "This is likely due to the complexity of the IR/IGF-1R signalling axis, compensatory mechanisms through other receptors, and a lack of predictive tumour- and patient-selective biomarkers of response." (PMID 27472395, 2016).